GSR (glutathione-disulfide reductase)
Diseases named in the same sentence as GSR in open-access papers (continued):
Sharing a sentence is not in itself a finding about the gene and the disease.
Allergy (1 paper, 2022). An allergy is an immune response or reaction to substances that are usually not harmful. "Several top-ranking genetic perturbagens including PAK1, GSR, RBM15 and TNFRSF12A have been indicated by previous studies to be involved in allergy/asthma." (PMID 35606385, 2022).
atherosclerosis (1 paper, 2013). A disease characterized by the build-up of fatty material and calcium deposition in the arterial wall resulting in partial or complete occlusion of the arterial lumen. "Further studies show that blueberry supplementation attenuated atherosclerosis by upregulating expression of the antioxidant enzymes SOD1, SOD2, GSR, and thioredoxin reductase- (TR-) 1 in ApoE deficient mouse models of atherosclerosis." (PMID 23691264, 2013).
breast tumors (1 paper, 2023). "Next, TCGA database indicated that all mRNAs encoding HO-1, CISD2, SOD-1 and GSR in breast tumors were significantly higher than those in normal tissues." (PMID 37217939, 2023).
cataract (1 paper, 2025). Partial or complete opacity of the crystalline lens of one or both eyes that decreases visual acuity and eventually results in blindness. "For instance, human patients with mutations in the GSR gene can reach old age, although they suffer hemolytic anemia, cataracts, deafness, and hyperbilirubinemia." (PMID 40333285, 2025).
fungal infections (1 paper, 2025). "GSR knockout mice do not show any phenotype under stabulary conditions but are highly sensitive to bacterial and fungal infections." (PMID 40333285, 2025).
gingivitis (1 paper, 2025). A disorder involving inflammation of the gums; may affect surrounding and supporting structures of the teeth. "The reduction of oxidative stress markers, as evidenced by the downregulation of antioxidant enzymes, such as SOD2 and GSR, supports the hypothesis that SnF2 can effectively mitigate the inflammatory state associated with gingivitis and reduce oxidative stress." (PMID 41156831, 2025).
hereditary anemia (1 paper, 2023). "Mutations in GSR appear to cause changes in the structure and function of the GSR protein, which may be associated with obstructive heart defects and hereditary anemia." (PMID 37175751, 2023).
lymph node metastasis (1 paper, 2018). "Besides, glutathione-disulfide reductase (GSR), human leukocyte antigen complex P5 (HCP5), and achaete-scute family bHLH transcription factor 1 (ASCL1) were upregulated in the SCLC patients with lymph node metastasis." (PMID 30364292, 2018). "Here, 186 upregulated (e.g., GSR, HCP5) and 144 downregulated DEGs (e.g., MET, GRM8, and DACH1) were identified between the SCLC patients with lymph node metastasis and without lymph node metastasis." (PMID 30364292, 2018).
malaria (1 paper, 2014). Malaria is a serious and sometimes fatal disease caused by a parasite that commonly infects a certain type of mosquito which feeds on humans. "Numerous studies have reported on associations of the genetic variants in GSR, GCLC, HMOX1 and SOD2 with oxidative stress related disorders and conditions including malaria." (PMID 24693973, 2014). "In conclusion, the present study has identified several polymorphisms in GCLC, GSR and HMOX1 genes that are associated with oxidative stress status in the blood plasma of two-year old children from a malaria endemic region." (PMID 24693973, 2014). "In case of an association between the GSR polymorphisms and a low anti-oxidant glutathione reducing activity, increased AOPP values would be the direct consequence of any inflammatory response or oxidation by the malaria parasite growing in RBCs." (PMID 24693973, 2014).
male infertility (1 paper, 2024). The inability of the male to effect fertilization of an ovum after a specified period of unprotected intercourse. "In our proteomics analysis, SOD2 and PRDX5 were underexpressed, while GSR was overexpressed, underscoring their potential significance in the pathophysiology of male infertility." (PMID 39726694, 2024). "Specifically, three mitochondrial proteins (GSR, PRDX5, and SOD2) exhibited expression patterns that have not been previously documented in the context of male infertility." (PMID 39726694, 2024).
malnutrition (1 paper, 2024). Inadequate nutrition resulting from poor diet, malabsorption, or abnormal nutrient distribution. "That humans can be rather robust toward reduced GSR activity is also exemplified by the high frequency of moderate GSR deficiency due to malnutrition, specifically due to the lack of riboflavin, which is a precursor of the GSR cofactor flavin adenine dinucleotide (FAD) in some populations." (PMID 38397443, 2024).
oral cancer (1 paper, 2021). "In the current study, antioxidant gene expressions (NFE2L2, SOD1, TXN, GSR, CAT, and GPX1) in oral cancer Ca9-22 and CAL 27 cells were highly downregulated by UVC/sinularin combined treatments compared to the separate treatments." (PMID 34070049, 2021). "Accordingly, the gene expressions of antioxidant genes such as NFE2L2, SOD1, TXN, GSR, CAT, and GPX1 were evaluated by qRT-PCR following UVC and/or sinularin treatments in oral cancer cells (Ca9-22 and CAL 27)." (PMID 34070049, 2021).
osteosarcoma (1 paper, 2023). A usually aggressive malignant bone-forming mesenchymal neoplasm, predominantly affecting adolescents and young adults. "GSR was found to be upregulated in an osteosarcoma cell line, as well as a decreased cell proliferation rate in osteoblasts from osteoporotic tissue." (PMID 37107290, 2023).
prostate tumors (1 paper, 2016). "Another lncRNA involved in glutamine metabolism is PCGEM1 an androgen-induced prostate specific lncRNA, which regulates expression of enzymes such as GLS, Glutathione Reductase (GSR), and type I gamma-glutamyltransferase (GGT1) in prostate tumors." (PMID 27551267, 2016).
pulmonary fibrosis (1 paper, 2025). Chronic progressive interstitial lung disorder characterized by the replacement of the lung tissue by connective tissue, leading to progressive dyspnea, respiratory failure, or right heart failure. "In summary, GSR deficiency exacerbates and promotes pulmonary fibrosis by inhibiting GSH levels and increasing the accumulation of ROS, thereby activating the TGF-β/Smad2 signaling pathway, suggesting GSR is a potential therapeutic target for IPF." (PMID 40723921, 2025). "In conclusion, our findings demonstrate that GSR deficiency aggravates pulmonary fibrosis by impairing antioxidant defense mechanisms, promoting EMT, and activating fibroblasts through the TGF-β/Smad2 signaling." (PMID 40723921, 2025). "To further elucidate the potential involvement of GSR in pulmonary fibrosis, we examined its response to the differentiation of lung fibroblasts into myofibroblasts induced by TGF-β." (PMID 40723921, 2025). "To delve deeper into the role of GSR in pulmonary fibrosis, we established an AECII-fibroblast coculture system." (PMID 40723921, 2025). "The findings suggest that reduced GSR expression could enhance the activation of pulmonary fibrosis by elevating ROS levels as part of the aging process." (PMID 40723921, 2025). "In this investigation, suppressing GSR expression led to a substantial rise in ROS concentrations within lung epithelial cells, paving the way for ROS-mediated injury to these cells and initiating pulmonary fibrosis." (PMID 40723921, 2025). "To further elucidate the role of GSR in pulmonary fibrosis, we posited that GSR might contribute to abnormal AECII injury and repair, potentially leading to dysregulated interactions between AECII and mesenchymal cells." (PMID 40723921, 2025). "This study identified decreased GSR expression in both IPF patients and BLM-treated murine models, prompting investigation into its functional role in pulmonary fibrosis." (PMID 40723921, 2025). "Mechanistically, GSR disruption boosts intracellular ROS levels and then activates the TGF-β/Smad2 pathway, shedding light on the key mechanism in oxidative stress-induced pulmonary fibrosis and providing new understanding for managing age-related diseases." (PMID 40723921, 2025).
Renal cyst (1 paper, 2024). A fluid filled sac in the kidney. "Levels of GSH biosynthetic enzymes were also downregulated in renal cysts, including the catalytic subunit of the rate-limiting enzyme glutamyl cysteine ligase (GCLC, −2.5×), glutathione synthetase (GSS, −1.9×), and glutathione reductase (GSR, −2.3×)." (PMID 39000280, 2024).
cancer (31 papers, 2014 to 2025). A tumor composed of atypical neoplastic, often pleomorphic cells that invade other tissues. "Protein expression data corroborate this finding, as in the five types of cancer, GSR expression was detected within medium to high levels." (PMID 39594421, 2024). "For example, SLC27A5 is downregulated in HCC, enhancing sora-induced ferroptosis by inhibiting the NRF2/GSR pathway in cancer cells, presenting a potential therapeutic approach to overcome sora resistance." (PMID 39548421, 2024). "Next, to evaluate GSR as putative target, we used 2-AAPA, an inhibitor of GSR that has shown anticancer activity in many cancer cell lines." (PMID 33498690, 2021). "There was variation in expression of SOD2, PRDX1 and GSR that didn’t correlate across the cancer cell lines and fibroblast." (PMID 33669867, 2021). "Hence, targeting TrxR in LUAD and perhaps other cancer patients is a new therapeutic option, given the frequent deletion of chromosome 8p12, where the GSR gene is located, in different cancers." (PMID 39061847, 2024). "GSR, Glutathione-Disulfide Reductase, has been extensively researched in a variety of cancers." (PMID 37168510, 2023). "GSR gene in human is located in chromosome 8p12, which is usually lost in cancers." (PMID 34107852, 2021). "Thus, GSR inhibition could facilitate ATO-mediated oxidation of intracellular proteins resulting in a synergistic induction of apoptosis in cancer cells." (PMID 30908483, 2019). "GPx level was substantially elevated in carcinoma tissues of FIGO I/II stages (+1.3-fold), whereas GSR expression was diminished independently of FIGO grade (FIGO I/II: −0.67-fold; FIGO III/IV: −0.52-fold)." (PMID 38397798, 2024). "Antioxidant enzymes, such as TXNRD, glutathione reductase (GSR), and xCT/SLC7A11, are commonly up-regulated in cancer cells to counteract the unwanted oxidation derived from metabolism." (PMID 37836684, 2023). "Based on these data, we propose the engagement of GSR in the TRAIL apoptotic pathway in, at least some, cancer cells." (PMID 26075913, 2015). "Given the importance of ROS generation to the mechanism of mitoKv1.3 inhibitor mediated cell death, it is not surprising to see that cancer cells resistant to PCARBTP upregulated the antioxidant system (GSR, GSTO1, GSTA2, ALDH3A1)." (PMID 35681598, 2022). "We further verified the expressions of the oxidative stress-responsive genes and the cholesterol biosynthesis-related genes using qPCR in the GBM cancer cells and recorded an increase in the mRNA levels of HMGCR, HMCGS1, DHCR24, GSR, GSTM2 and GCLC after MPT0L145 treatment in U87MG and M059K cells." (PMID 34885226, 2021). "We recently reported the discovery of 1,4-naphthoquinine (1,4-NQ) derivative, NSC130362, which inhibits GSR and, as a consequence, induces oxidative stress and subsequent apoptosis in cancer cells but not in normal human primary hepatocytes." (PMID 30908483, 2019). "Recently, we published that NSC130362 inhibits GSR and, as a consequence, induces ROS and subsequent apoptosis in cancer cells but not in normal human hepatocytes as a model for hepatotoxicity." (PMID 30908483, 2019). "Upper panel, silencing GSR gene expression potentiated TRAIL activity in cancer cells but not in human primary hepatocytes." (PMID 26075913, 2015). "Also WA regulates the activity of antioxidant enzymes (such as superoxide dismutase) and mRNA expression of antioxidant genes: erythroid 2-like 2 (NFE2L2), heme oxygenase 1 (HMOX1), glutathione-disulfide reductase (GSR), and NAD(P)H quinone dehydrogenase 1 (NQO1)) in cancer cells." (PMID 33498013, 2021). "Interestingly, when the 6-position primary amino group of compound 64 was replaced by an anilino group, creating compound 67, a well-known GSR inhibitor LY83583, anti-cancer activity increased approximately 10-fold, while toxicity to hepatocytes was decreased 3-fold." (PMID 30908483, 2019).
cancer (continued). "In our study we identified a specific inhibitor of GSR activity, which, when combined with other oxidative stress inducers, may provide the basis for a potent and non-toxic cancer therapy." (PMID 26075913, 2015). "In the overall cohort, ZFPM2 rs4734879, SLC19 A2 rs2038024, ITGB3 rs5918 and GSR rs3779647 did not exhibit a significant impact on five-year DFS, regardless of genetic model (additive, recessive or dominant), sex (male vs. female) and cancer stage (III/IV vs. I/II or I/II/III vs. IV)." (PMID 40425987, 2025).
tumor (20 papers, 2015 to 2025). "Using the Gr1a1Neu allele which is a whole-body knockout (KO) allele of GSR, we generated KrasG12D/+; Nrf2+/+; Gsra1Neu/a1Neu (GSR KO) and KrasG12D/+; Nrf2D29H/+; Gsra1Neu/a1Neu (GSR KO) lung tumors to evaluate the requirement of GSR for tumor initiation and progression." (PMID 40334547, 2025). "We focused on TXNRD1 and GSR, the key mediators of the thioredoxin- and glutathione-dependent systems, and deleted these enzymes alone or in combination to study their roles in tumor initiation and early progression." (PMID 40334547, 2025). "Like what we observed in the GSR KO model, we found that TXNRD1/GSR DKO significantly reduced tumor number (tumor initiation) in both the KrasG12D/+, Nrf2+/+ mice and KrasG12D/+, Nrf2D29H/+ models." (PMID 40334547, 2025). "We found that GSR KO significantly decreased tumor number in both the KrasG12D/+; Nrf2+/+ and KrasG12D/+; Nrf2D29H/+ models." (PMID 40334547, 2025). "Based on our results, the combination of sorafenib and carmustine (BCNU), a selective inhibitor of GSR, remarkably hamper tumor growth by enhancing ferroptotic cell death in vivo." (PMID 36635256, 2023). "We also found a small but a significant decrease in the glutathione reductase gene (GSR) following TPT exposure in MCF-7 tumor cells." (PMID 32765594, 2020). "Can some LAR tumors escape cisplatin by upregulating its transport out of the cell while others escape by different mechanisms such as upregulating GSR, or does a single tumor tend to accumulate multiple mechanisms of resistance?" (PMID 31684899, 2019). "In a previous study, GSR expression level was significantly increased in tumor tissue from patients with LC." (PMID 30364292, 2018). "Moreover, the tumor mRNA expression of glutathione S-reductase (GSR) and superoxide dismutase 1 (SOD1) showed a trend of increase, whereas catalase (CAT) was significantly downregulated." (PMID 33668151, 2021). "NRF2-dependent antioxidant enzymes such as SOD, glutathione peroxidase (GPX), glutathione reductase (GSR), peroxiredoxin (PRX), and thioredoxin reductase (TXNRD) are upregulated in tumor cells, and high expression of these proteins is associated with poor prognosis in tumor patients." (PMID 31929797, 2019). "Taken together e.g., modulations of FXDR, MSR, GSR, and GPx genes by TPT in MCF-7 (and ZR-75-1) tumor cells strongly indicate formation of ROS and induction of cellular imbalance of homeostasis, resulting in increased oxidative stress by TPT." (PMID 32765594, 2020). "We found that tumor initiation was promoted by expression of GSR, but not TXNRD1, regardless of Nrf2 status." (PMID 40334547, 2025). "When interpreting results from this study, it is also important to note that GSR activity is also lacking in the tumor microenvironment in addition to the lung tumor cells." (PMID 40334547, 2025). "Moreover, the promoter activities of GCLC, GSR, PRDX1, and MSRA were significantly elevated in HFD tumor cells compared to LFD cells." (PMID 35182054, 2022). "Inhibition of GSR and TXNRD attenuated tumor growth in an NSCLC patient-derived xenograft model." (PMID 31929797, 2019). "Future work targeting GSR KO to only the lung tumor cells, and combining it with inhibition of GSH synthesis will reveal whether inhibition of both GSH synthesis and recycling within the tumor cells abolishes the Nrf2-mediated tumor initiation phenotype." (PMID 40334547, 2025). "Furthermore, histological examinations showed that levels of YAP, GSR, and GCLC proteins were concomitantly elevated in Py8119 tumor tissues from obese mice, compared to those in lean mice, but increased expressions of YAP, GSR, and GCLC were reduced by YAP‐knockdown." (PMID 35182054, 2022).
tumor (continued). "In addition, both CM presented a remarkable quantity of different proteins that have been associated with antioxidant and/or anti-inflammatory effects and may thus mediate the viability of non-tumor cells, such as AIFM1, ANXA5, CD9, CDH13, GDF15, GSR and TIMP2." (PMID 34884877, 2021). "Simultaneous deletion of GSR and TXNRD1 reduced initiation and progression independent of Nrf2 status, but surprisingly did not completely abrogate tumor formation." (PMID 40334547, 2025).
infection (6 papers, 2016 to 2025). The state of being infected such as from the introduction of a foreign agent such as serum, vaccine, antigenic substance or organism. "Consistent with a central role for oxidative stress responses in cell-intrinsic responses to infection, key antioxidant enzymes (GSR, CAT, GPX1, and PRDX1) were downregulated by YFV-17D and select genes (SOD2, NFE2L2, and KEAP1) were upregulated by MnTBAP treatment." (PMID 39282299, 2024). "The results displayed that RES significantly increased the mRNA levels of Nrf2 and its target genes, including γ-GCS, SLC7A11, and GSR, compared with the ASFV-WT infection group at 12, 24, and 48 hpi." (PMID 39964001, 2025).
GSR also shares sentences with these, for which no sentence is quoted: epilepsy (3 papers); major depressive disorder (3); encephalitis (2); liver cancer (2); Parkinson disease (2); psychiatric disorder (2); Stroke (2); Alzheimer disease (1); amyotrophic lateral sclerosis (1); Astrocytoma (1); autoimmune encephalitis (1); bipolar disorder (1); brain cancer (1); cardiac hypertrophy (1); cerebellar ataxia (1); Cerebral ischemia (1); deafness (1); demyelinating disease (1); depression (1); frontotemporal dementia (1); Hearing impairment (1); hemoglobinopathies (1); Hyperbilirubinemia (1); Hyperglycemia (1); Insulin resistance (1); ischemia (1); memory impairment (1); muscular disease (1); myocardial infarction (1); myopathy (1).
A further 6 diseases each share a sentence with GSR in 1 paper.